ARID1A (AT-rich interaction domain 1A)
Diseases named in the same sentence as ARID1A in open-access papers (continued):
Sharing a sentence is not in itself a finding about the gene and the disease.
ovarian clear cell cancer (continued). "In ARID1A-mutant colorectal cancer and ovarian clear cell carcinoma, many enhancers lose SWI/SNF binding and cannot stimulate gene expression." (PMID 36435834, 2022). "The therapeutic utility of EZH2 has been explored extensively in ovarian clear-cell cancer (OCCC), another gynecologic cancer with high rates of ARID1A mutation." (PMID 35326450, 2022). "Although ovarian clear cell carcinoma was represented in a minor proportion, PIK3CA and ARID1A genes were found mutated in two of the three studied cases." (PMID 36010253, 2022). "Co-occurrence of ARID1A alterations with PI3K/AKT pathway activation has been reported in ovarian clear cell carcinoma, breast cancer, and gastric cancer." (PMID 35070505, 2022). "In ovarian clear-cell carcinomas, 40% of tumors harbor PIK3CA somatic mutations and the majority of these were ARID1A-deficient tumors." (PMID 35070505, 2022). "The highest ARID1A mutation rates are found in ovarian clear cell carcinoma (OCCC) and endometroid ovarian carcinoma suggesting its role in type I OC development and the potential for ARID1A’s use as a gynecologic cancer biomarker." (PMID 36430148, 2022). "ARID1A is an epigenetic regulator that is mutated in nearly 6% of cancers, including HCC, ovarian clear cell cancers, uterine endometrioid cancers, and gastric cancers." (PMID 35669430, 2022). "Both GAS5 and ARID1A (AT-rich interactive domain 1A) are underexpressed in ovarian clear cell carcinoma (OCCC)." (PMID 35837102, 2022). "Several studies suggest the cross-talk between the ARID1A and PI3K pathways in clear cell ovarian cancer and have shown that synthetic lethality by targeting EZH2 in ARID1A-mutated tumors correlates with inhibition of PI3K/AKT signaling." (PMID 35852858, 2022). "The synthetic lethality of ARID1A and AURKA has been further demonstrated in ARID1A-deficient ovarian clear cell carcinoma (OCCC) cells and in mouse tumor xenograft models of CRC83." (PMID 34050264, 2021). "Loss of ARID1A was reported to be associated with increasing TMB, TILs, and PD-L1 expression in ovarian clear cell carcinoma and gastric carcinoma, and patients with ARID1A deficiency had a higher response rate to immunotherapy." (PMID 35145511, 2021). "ARID1A have since been observed at high frequency in a number of studies, including uterine and ovarian clear cell carcinoma (46–57%), ovarian endometrioid carcinoma (30%), and uterine endometrioid carcinoma (47–60%)." (PMID 34680987, 2021). "In turn, 27% of ARID1A heterozygous ovarian clear cell carcinomas exhibited detectable protein expression." (PMID 34200508, 2021). "Molecular profiling of human endometrioid ovarian cancers revealed that the most prevalent mutations are similar to those observed in clear-cell ovarian cancer and include PIK3CA (40%), ARID1A (30%), KRAS (30%), PTEN (16%), and PPP2R1A (16%)." (PMID 32679669, 2020). "On the other hand, our recent studies clarified that cancer-associated genes such as ARID1A, PIK3CA and KRAS are frequently mutated not only in ovarian clear cell carcinoma but also in ovarian endometriosis." (PMID 32868822, 2020). "Two major genes reported to be mutated in ovarian clear cell carcinoma are PIK3CA and ARID1A, which frequently coexist with each other." (PMID 31731647, 2019). "AT-rich interaction domain 1A (ARID1A) and phosphatidylinositol-4,5-3-kinase catalytic subunit alpha (PIK3CA) mutations characterize a majority of ovarian clear-cell carcinomas, while low-grade serous ovarian tumors predominantly show alterations in KRAS." (PMID 31817625, 2019). "Low ARID1A expression has been linked with poor outcome and platinum resistance in HGSOC and clear-cell ovarian cancers." (PMID 29669295, 2018). "Loss of ARID1A and PIK3CA was a common finding in 130 cases of ovarian clear cell carcinoma (56.2% and 45.0%, resp)." (PMID 29743986, 2018). "ARID1A, PIK3CA, CTNNB1, PTEN, and KRAS are commonly mutated in both endometrioid and clear cell ovarian cancers from women." (PMID 30087267, 2018).
ovarian clear cell cancer (continued). "Inactivating mutations in ARID1A, which encodes a subunit of the SWI/SNF chromatin-remodeling complex, are found in over half of ovarian clear cell carcinoma cases and more broadly across most types of cancers." (PMID 27654507, 2016). "Consistent with our in vitro findings, we found that ovarian clear cell carcinoma patient samples with low ARID1A expression exhibited increased oxidative stress." (PMID 27486766, 2016). "In ovarian clear cell carcinoma patient samples, low expression of ARID1A correlated with high expression of 8-hydroxyguanosine, a marker for oxidative stress." (PMID 27486766, 2016). "For example, a synergistic oncogenic event triggered by ARID1A loss and PIK3CA activation leads to ovarian clear cell carcinoma in an animal model." (PMID 26716708, 2015). "Recent whole genome or targeted sequencing studies have identified frequent mutations of ARID1A and PIK3CA genes, and moderate mutations of PPP2R1A and KRAS in ovarian clear cell carcinomas, mutations of PTEN, CTNNB1 and KRAS in endometrioid cancer." (PMID 23466883, 2013). "Consistent with our findings, other investigators also found that decreased ARID1A expression is significantly associated with a higher grade of breast cancer, as well as a higher FIGO stage in ovarian clear cell carcinoma." (PMID 22808142, 2012). "In ovarian clear cell carcinoma, it was also reported that patients with positive ARID1A expression had a longer progression-free survival than those with negative ARID1A expression." (PMID 22808142, 2012). "Mutations have been described in other members of the same family, such as ARID1A in around 50% of ovarian clear cell carcinomas and in gastric cancer, and SMARCA4/BRG1 in lung tumors." (PMID 22675518, 2012). "Recent genome-wide sequencing analyses of all exons and transcriptome in ovarian clear cell carcinomas (OCCC) have identified somatic mutations of ARID1A (the AT-rich interactive domain 1A), also known as BAF250, in approximately half of OCCC cases." (PMID 21614196, 2010). "We then performed immunohistochemistry to assess ARID1A expression patterns on paraffin sections from a total of 149 cases of ovarian clear cell carcinoma with well annotated clinical follow up information." (PMID 21614196, 2010). "Furthermore, when using in vivo models of ARID1A- and PIK3CA-mutated ovarian clear cell carcinoma, treatment with an HDAC6 inhibitor reduced tumor growth and improved survival rates by promoting the activation of IFN gamma-positive CD8 T cells." (PMID 41514650, 2025). "It is the most frequently mutated subunit of the SWI/SNF complex, with inactivating mutations found in 6% of cancers, including ovarian clear cell cancers (45% of cases), uterine endometrioid cancers (37%) and hepatocellular carcinoma HCC (14%), highlighting the roles of ARID1A in cancer." (PMID 39471843, 2024). "This is the case for the gene ARID1A which is lost in about 50% of ovarian clear cell carcinomas." (PMID 39272807, 2024). "In ARID1A-inactivated ovarian carcinoma clear cell carcinoma (OCCC), the loss of ARID1A increases glutamine utilization and metabolism through upregulation of the expression of glutaminase (GLS1), a key enzyme in glutamine metabolism that is overexpressed in several human cancers." (PMID 36980292, 2023). "In mice models, separate ARID1A or PI3K/AKT pathway mutations promoted ovarian hyperplasia, while concomitant inactivation of ARID1A together with PIK3CA activating mutations induced tumors, similar to ovarian clear cell carcinoma (OCCC)." (PMID 36430148, 2022). "ARID1A generally acts as a tumour suppressor gene which is lost in as many as 7% of all cancers, including at very high frequency in certain ovarian cancers (e.g. 50% in clear cell ovarian cancers)." (PMID 33826602, 2021).
ovarian clear cell cancer (continued). "ARID1A mutations were found in 46% (55/119) of ovarian clear cell carcinomas, in 30% (10/33) of endometrioid carcinomas, but in none of serous carcinomas." (PMID 29743986, 2018). "More recent studies of exome sequencing performed on clear-cell ovarian cancer samples have provided definitive evidence that chromatin remodeling and PI3K are major drivers in clear cell carcinomas, with frequencies of ARID1A gene mutations of 60–65% and PIK3CA of 50–52%." (PMID 29389895, 2018). "In general, both endometrioid and clear cell ovarian cancer with or without endometriosis have common high frequency mutations in ARID1A, PIK3CA, catenin betat 1 (CTNNB1), PTEN, and KRAS." (PMID 30087267, 2018). "ARID1B function at enhancers is conserved in ARID1A mutant ovarian clear cell carcinoma cells." (PMID 28967863, 2017). "Knockout of ARID1A in an ovarian clear cell carcinoma cell line with wild-type ARID1A, OVCA429, primarily resulted in downregulation of the mevalonate pathway, an important metabolic pathway involved in isoprenoid synthesis, cholesterol synthesis, and other downstream pathways." (PMID 27654507, 2016). "In particular, AT-rich interactive domain-containing protein 1A (ARID1A) is the most frequently mutated SWI/SNF subunit in cancer, with the highest mutation frequency in gynecologic cancers, i.e. ovarian clear cell carcinomas, ovarian endometrioid carcinomas, and endometrial endometrioid carcinomas." (PMID 27486766, 2016). "Both clear cell ovarian carcinomas (CCC) and ovarian endometrioid carcinomas (EC) may arise from endometriosis and frequently harbor mutations in the ARID1A tumor suppressor gene." (PMID 24559118, 2014). "ARID1A (AT-rich interaction domain 1A), a subunit of the BAF complex, has been identified as one of the most frequently mutated tumor suppressors in a variety of cancers, with the highest mutation frequency in ovarian clear cell carcinoma (OCCC) and endometrial cancer." (PMID 40369167, 2025). "In the mouse model, ovarian tumors with similar features to ovarian clear cell carcinoma were only developed when with ARID1A/PI3K double mutations, but not with only a single ARID1A or PI3K mutation, suggesting the effects the cooperation of these two genes have in cancer." (PMID 34680987, 2021). "Certain mutations, such as ARID1A mutations, and alterations in the phosphatidylinositol 3-kinase (PI3K)/AKT/mTOR pathway, which are specific in ovarian clear cell carcinoma (OCCC) and endometrioid ovarian carcinoma (EnOC), may offer additional therapeutic targets in these clinical entities." (PMID 32455595, 2020). "Finally, we compared the clinicopathological features of ovarian clear cell carcinoma with ARID1A loss-of-function mutations to those of ovarian clear cell carcinoma without ARID1A mutations." (PMID 32868822, 2020). "Ovarian clear cell carcinomas (OCCC), particularly cases that retain wild-type AT-rich interactive domain 1 A (ARID1A) expression (approximately 50% of the OCCC cases), are chemoresistant and lack specific therapies." (PMID 41933240, 2026). "For example, ARID1A directly binds to the TERT promoter region and suppresses TERT expression by promoting chromatin condensation in ovarian clear cell carcinoma." (PMID 41049615, 2025).
ovarian clear cell cancer (continued). "In a study of ovarian clear cell carcinoma (OCCC) cells, researchers mined published ChIP-seq data and found that SWI/SNF subunits such as ARID1A, SNF5, SMARCA4, and BAF155 can directly bind to GLS1." (PMID 39609317, 2024). "OVTOKO, OVISE, and OVMANA are considered clear-cell ovarian cancer cell lines as they were derived from metastatic lesions of OCCC and contain a mutant ARID1A." (PMID 37621654, 2023). "For instance, reduced ARID1A expression has been correlated with the FIGO (International Federation of Gynecology and Obstetrics) stage, shorter progression-free survival in ovarian clear cell carcinoma, endometrium-related cancers, and cervical cancer." (PMID 36123603, 2022). "A synthetic lethal relationship between ARID1A and ARID1B has previously been observed for proliferation of ovarian clear cell carcinoma cells (OCCCs)." (PMID 28967863, 2017). "Among the 69 ovarian clear cell carcinoma cases analyzed, PTEN expression was negative in 78.3% (54/69) of cases, while ARID1A loss was observed in 48.8% (39/69) of cases." (PMID 40430056, 2025). "Unlike ovarian clear cell carcinoma, cervical adenocarcinomas, and gastric carcinoma, SCLC harbored a relatively low frequency of ARID1A and ARID1B mutations." (PMID 41049615, 2025). "We used genetic screening to identify targets for killing an ovarian clear cell carcinoma cell line lacking the ARID1A gene." (PMID 39272807, 2024). "Drug development targeting ARID1A and PIK3CA in clear-cell ovarian carcinomas is also warranted." (PMID 38201563, 2023). "Alterations in ARID1A gene occur in about 6% of cancers, including but not limited to clear cell ovarian cancers (45%), endometrial cancers (37%), gastric cancers (20–30%), and bladder cancers (20%)." (PMID 37711591, 2023). "In the ovarian clear cell carcinoma (OCCC), people discovered that ARID1A WT OCCCs enhanced Th1-type immune responses, cytotoxic T cell responses, and NK cell activation, but ARID1A mutant OCCCs lacked type II and type I IFN signaling pathways, but the latent mechanism needs to discover." (PMID 35518785, 2022). "Instead, they have mutations in “non-HGSOC” genes: ARID1A (mutation typical for clear cell and endometrioid ovarian cancers) and PI3K (frequently found in clear cell ovarian cancers)." (PMID 30018258, 2018). "To identify ARID1A-dependent changes in intracellular signaling pathways, we performed proteome analyses of isogenic ovarian clear cell carcinoma cell lines with or without ARID1A expression." (PMID 27654507, 2016). "For instance, ARID1A is known to promote the formation of SWI/SNF chromatin remodeling complexes containing BRG1 or BRM, and is a candidate tumor suppressor not only in clear cell ovarian cancer but also in endometrioid cancers and uterine endometrioid carcinomas." (PMID 25551281, 2014). "However, Dex-induced RNA Polymerase II intragenic enrichment was unaffected, consistent with reported findings of increased RNA Polymerase II stalling/pausing without an effect on transcriptional initiation in ovarian clear cell carcinoma cells lacking ARID1a." (PMID 36344675, 2022).
gastric cancer (155 papers, 2012 to 2026). A primary or metastatic malignant neoplasm involving the stomach. "By contrast, PBRM1 loss in renal cell carcinoma is associated with primary ICIs resistance, and ARID1A deficiency in gastric cancer promotes aggressive metastatic behavior." (PMID 41438758, 2025). "Mutations in ARID1B, the paralog of ARID1A, have also been identified in diverse tumor types such as ovarian, lung, and gastric cancers." (PMID 40087883, 2025). "ARID1A is a frequently mutated gene in gastric cancers (GCs), particularly in those associated with the Epstein-Barr virus (EBV), which also often shows PIK3CA mutations and CDKN2A silencing." (PMID 40761291, 2025). "A subsequent study on gastric cancer supported this finding, demonstrating an inverse relationship between ARID1A and PD-L1 expression while linking ARID1A loss to an increased tumor mutation burden." (PMID 40429787, 2025). "In a subsequent study, ARID1A mutations in gastric cancer patients also increased mutation rates in many other cancer-related genes compared to patients with normal ARID1A." (PMID 40429787, 2025). "In conclusion, in this comprehensive review, we have focused on detailing the clinical significance, predictive value, underlying mechanisms, and potential treatment strategies for ARID1A mutations in gastric cancer." (PMID 38893181, 2024). "Then, successive studies have shown that ARID1A mutations are also present in other cancers, such as 29% in gastric cancer, 10-17% in hepatocellular carcinoma, 10% in colorectal cancer, and 13% in bladder cancer." (PMID 39697230, 2024). "ARID1A mutations are relatively common in gastric cancer, particularly in specific adenocarcinoma subtypes." (PMID 38893181, 2024). "Reduced solute carrier family seven-member 11(SLC7A11) recombinant protein expression decreases GSH synthesis, making ARID1A-deficient stomach cancer cells vulnerable to GSH inhibition." (PMID 38008753, 2023). "Their study revealed that ARID1A is a gene targeted by miR‐7641, and in gastric cancer tissues, high levels of miR‐7641 are linked to low ARID1A expression." (PMID 38041544, 2023). "A systematic meta-analysis of fourteen studies demonstrated that the loss of ARID1A expression predicts poor overall survival in gastric cancer, specifically in Asian populations suggesting a potential role as prognostic biomarker." (PMID 36890819, 2023). "Previous studies have found that ARID1A mutations are likely to be related to the higher immune infiltrates in endometrial cancer, stomach cancer and colon cancer." (PMID 37301854, 2023). "ARID1A mutation or deficiency has been shown to contribute to facilitating the aggressiveness of tumors, and it has been identified that most gastric cancer patients carry ARID1A mutations." (PMID 37215622, 2023). "A study confirmed that loss of ARID1A in EBV‐positive gastric cancer was partly regulated by EBV‐encoded miRNAs21; meanwhile, ARID1A loss increased the susceptibility of gastric epithelial cells to EBV infection and promoted gastric tumorigenesis." (PMID 37366273, 2023). "This approach has the potential to lead to more effective and personalized treatments for individuals with ARID1A‐mutated gastric cancer and other cancers with similar genetic changes." (PMID 38041544, 2023). "Epstein–Barr virus‐positive gastric cancer frequently shows mutations in ARID1A and PIK3CA and has a more distinct CpG methylation profile when compared to MSI‐type GC." (PMID 38041544, 2023).